CD4 (CD4 molecule)
Diseases named in the same sentence as CD4 in open-access papers (continued):
Sharing a sentence is not in itself a finding about the gene and the disease.
Immunodeficiency (continued). "The expression of TNFAIP8 also affects the polarization of splenic CD4+ T lymphocytes after sepsis, suggesting that TNFAIP8 regulates the pathogenesis of splenic T lymphocyte immune dysfunction in mice." (PMID 34925463, 2021). "We report in this article for the first time, to our knowledge, that As2O3 can modulate CD4+CD25+ Treg-cell differentiation and affect its function, thus improving immune dysfunction." (PMID 34108876, 2021). "Clinical trials in immunodeficiency, autoimmune diseases, and infectious diseases show that Biomodulina T restores CD3+, CD4+, and CD8+ T-cells and their function and enhances the immune response against infections." (PMID 33362793, 2020). "Some studies have found that CD4 remains relatively stable as long as viral suppression is maintained, whereas others have found significant CD4 loss and progression to a certain threshold of immune deficiency, considering a negative CD4 counts slope as an indicator of immunological progression." (PMID 32698654, 2020). "Several mechanisms have been suggested to contribute immune dysfunction in CHC, such as the immunoregulatory properties of HCV proteins, the availability of CD4 T cell help, and the increased number of CD4+ CD25+ Treg cells." (PMID 32108916, 2020). "Future studies of CD4+ T cell counts, P. falciparum-specific antibodies, and cytokine levels, for example, would increase our understanding of HIV-related immune dysfunction and increased gametocytemia." (PMID 33614525, 2020). "We found that well-treated PWH had residual immune dysfunctions with elevated proportions of CD8+ activation, CD4+ senescence, and CD4+ and CD8+ apoptosis even after adjusting for confounders including age, sex, BMI group, and smoking status." (PMID 33117394, 2020). "The balance of the CD4+ T cell and CD8+ T cell ratio is a necessary condition for maintaining normal immune function in the body, with an imbalance of the ratio leading to immune dysfunction." (PMID 33101444, 2020). "Our study shows that CD8+ T cells, CD4+ T effectors, and CD4+ Tregs all contribute to an increase in TNF-α in psoriatic skin, suggesting multiple elements of immune dysfunction." (PMID 30054515, 2018). "It is well-known that psoriasis is a T cell-, particularly a CD4+ and CD8+ T cell-mediated immune disease, but the function of neutrophils is much less well understood." (PMID 29871627, 2018). "Meanwhile, the ratio of CD4/CD8, a marker of immune dysfunction, in −VB6− group was significantly less than that in +VB6+ group (P < 0.05)." (PMID 28367454, 2017). "The data were supported by a higher ratio of CD4+/CD8+ T cells in the testis, which is comparable to many other immune disorders and diseases." (PMID 28205525, 2017). "Studies investigating whether aviremic HIV-2 infection is associated with increased CD4+ T-cell pathology remain, however, limited, and no study, to our knowledge, has shown whether immunodeficiency in aviremic HIV-2-infection is linked to altered memory CD4+ T-cell pathology." (PMID 27525551, 2016). "We identified immunodeficiency at each step in the HSV-2 pathogenesis cycle in men with HIV-1 and CD4<200/uL." (PMID 27285483, 2016). "CD4+ cell count at baseline was inversely related with per capita cost and this cost was particularly high in HIV+ subjects at advanced immunodeficiency stage, in agreement with previous studies." (PMID 27829390, 2016). "In scenarios involving immunodeficiency, such as human immunodeficiency virus (HIV) infection, depletion of CD4+ T cells increases the likelihood of Cryptococcus invasion of the blood-brain barrier to cause meningoencephalitis." (PMID 25492918, 2015). "In summary, prevalence of CD4+CD28− T cells is high in chronic inflammatory diseases, immunodeficiency, and specific infectious diseases." (PMID 25834833, 2015).
Immunodeficiency (continued). "The inverse relation observed between current CD4 count and TSH even after adjusting for variables highlights the possible link between increased immunodeficiency and elevated TSH." (PMID 26798547, 2015). "Various other immune disorders have been described in ICL patients, including low CD8+ T cells counts and defective expression of CXCR4 on the surface of CD4+ cells." (PMID 26491451, 2015). "This review focuses on the relevance of the CD4:CD8 ratio on clinical outcomes, immune dysfunction and HIV reservoir size in long-term treated patients." (PMID 26130226, 2015). "Our results have potential clinical implications for novel therapeutic strategies targeting immune dysfunction in chronically treated HIV-infected individuals, in particular those with persistent expansion of CD8+ T cells despite adequate CD4+ T cell recovery." (PMID 24831517, 2014). "Our data highlight the potential of epigenomics in the stratification of immune disease and represents the first successful molecular classification of SAR using CD4+ T cells." (PMID 24391521, 2014). "However, it is not entirely clear whether TB is causally related to death, a marker of HIV-associated immunodeficiency that is not reflected by CD4 cell counts or is simply an epiphenomenon among highly immunocompromised patients." (PMID 23418463, 2013). "Immunodeficiency is common in HIV positive patients admitted to ICU, with median CD4 cell counts of 39–195 cells/mm3 and HIV-related complications present in 21–81%." (PMID 23331544, 2013). "Previous studies have shown that although FIPV cannot infect CD4+ and CD8+ T-cells, cats infected with the virus showed T cell depletion by apoptosis resulting in an acute immunodeficiency." (PMID 24209771, 2013). "Reports show that absolute gains in weight, BMI, CD4 cell count, FFM and BCM are higher among patients with severe immunodeficiency, indicating that demonstrable improvements are most likely to be seen among the most immunosuppressed." (PMID 23919622, 2013). "As a mechanism of this immunodeficiency, HBZ has been shown to inhibit CD4 T-cell responses, resulting in impaired host immunity in vivo." (PMID 24359396, 2013). "Increases in CMV-Sp-CD4 with ART occurred early and were greater in those with more advanced immunodeficiency." (PMID 24130889, 2013). "Accordingly, FIV infection of the cat results in a progressive depletion of CD4+ helper T cells and the development of an AIDS-like immune dysfunction." (PMID 23992667, 2013). "More adults than children had severe immunodeficiency, likely reflecting earlier accrual (2003–2004 vs 2007–2008) and more stringent DART eligibility criteria of CD4 <200 cells/μL and symptomatic HIV disease." (PMID 22972859, 2012). "CD4+ and CD8+ T lymphocytes are the hub of immune regulation, and when the CD4+/CD8+ ratio is high but within the normal range, the body has a high immune status, whereas when the CD4+/CD8+ ratio is disrupted, this can lead to a variety of immune diseases." (PMID 23342387, 2012). "The median CD4+ T-cell percentage at ART initiation was 16.3% (IQR: 11.5, 20.1; 59.8% severe immunodeficiency)." (PMID 21362177, 2011). "Only 1 of 45 children age 3 to 5 years had CD4+ T-lymphocyte percentages ≤25% for this age group, the WHO threshold for immunodeficiency." (PMID 19944455, 2010). "CD4+CD25+ T regulatory cells (Tregs) play an important role in regulating immune responses, and in influencing human immune diseases such as HIV infection." (PMID 17688698, 2007). "We also found, upon further investigation, that the incidence rate of endemic HCoV infections among PLWH with immunodeficiency (CD4+ T cells ≤ 350 cell/mm3) was not significantly different from without immunodeficiency." (PMID 40531922, 2025). "22.99% (43/187) had CD4 + T - cell counts ≥ 500 cells/mm3 without obvious immunodeficiency, while 69.52% (130/187) demonstrated viral loads > 10,000 copies/mL." (PMID 41219372, 2025).
Immunodeficiency (continued). "In this study, we found that the average CD4+ T lymphocyte count was >400 cells/μL, with only ten cases having counts <200 cells/μL, suggesting that not all patients with diabetes exhibit immune dysfunction." (PMID 40109771, 2025). "Studies suggest that tissue-based CD4:CD8 ratios may remain altered despite normalized ratios in blood, reflecting compartmentalized immune dysfunction." (PMID 41149805, 2025). "Furthermore, both IFI16 and NLRP3 correlated negatively with CD4 T cell counts, indicating decreased levels in relation to HIV-related immunodeficiency." (PMID 39000248, 2024). "In our study, the PJP group showed the lower CD4+ T cell count compared with non-PJP group, which suggested that HIV positive patients had severe immune deficiency when PJP was confirmed." (PMID 39372273, 2024). "Immunodeficiency was significant in a patient diagnosed with primary hypothyroidism in the first year of age and in another patient with subclinical hypothyroidism, fetal growth, a reduction of CD3/CD8, and an increase of the CD4/CD8 ratio." (PMID 38990976, 2024). "Here we discuss two possible ranking systems, CD4/CD8 T cell ratios and Immune Health Grades, and how such data maybe applicable to some immunodeficiencies." (PMID 39728019, 2024). "Situations that increase mortality in individuals with KS are related to the severe state of immunodeficiency, as was the case in this cohort in whom the CD4/CD8 ratio was <0.1; this severe immunodeficiency environment is essential for human herpesvirus 8 to produce KS." (PMID 39568658, 2024). "The ratio of CD4+ T/CD8+ T cells in the peripheral blood of healthy adults and mice is approximately 2:1, and breaking the balance usually indicates diseases relating to immunodeficiency induced by an impaired immune system." (PMID 38263182, 2024). "Specifically, there was a positive correlation between nutritional risk and immune dysfunction, along with positive associations with the NLR and PLR, and negative associations with CD4+, CD8+, CD3+, and LYM counts." (PMID 39086487, 2024). "CD4+ T lymphocyte infiltrated in the colon of DSS-induced mice, that indicated the immune disorders in colitis, and that could be improved by SYD dramatically." (PMID 38879471, 2024). "The CD4 T-lymphocyte-mediated response is lower than the CD8 response in all groups of patients with immunodeficiency, but differences are not statistically significant (p = 0.070)." (PMID 38132279, 2023). "Mutations in the ZAP70 gene cause a combined immunodeficiency characterized by low or absent CD8+ T cells and nonfunctional CD4+ T cells." (PMID 37313400, 2023). "An increasing proportion of children and adolescents did not have a baseline CD4 count, and a substantial proportion were still initiating treatment with severe immunodeficiency." (PMID 37708128, 2023). "At re-engagement, our patient showed no signs of a hepatitis flare, probably due to his severe immunodeficiency and low CD4 cells count." (PMID 37124041, 2023). "Consequently, the ratios of CD4+ T cells to CD8+ T cells were lower among PJP patients (0.8 vs. 1.5; P = 0.0015), indicating that PJP patients have both immunodeficiency and hyperimmunity." (PMID 37986091, 2023). "It has been reported that approximately 81% of patients with disseminated NTM with no obvious immunodeficiency and normal CD4 lymphocyte counts are positive for anti-IFN-γ autoantibodies." (PMID 37495965, 2023). "By flow cytometry analysis, we found that both CD8+ T cells and CD4+ T cells have higher levels of exhaustion marker PD‐1 in CDVC patients, reflecting the immune dysfunction observed in CDVC patients, as the immune response is abnormally skewed towards immunosuppressive Th2 response." (PMID 37773701, 2023). "Most patients had mild, or no immunodeficiency as indicated by their total lymphocyte and CD4 + counts." (PMID 35690869, 2022). "This indicates that high level of CD4+ and CD8+MAIT cell might be involved in immune dysfunction during LC." (PMID 35371315, 2022).
Immunodeficiency (continued). "Apart from T-cell maturation, Zn also aids in the cell differentiation process, where it was observed that a deficiency of Zn demonstrated a decrease in CD4+ T cells, which ultimately results in the disruption of CD4+/CD8+ cells ratio, which is a characteristic sign of immune dysfunction." (PMID 35711754, 2022). "Moreover, AD is characterized by T cell abnormalities such as immunodeficiency-related and age-related decreases in the CD3+CD4+/CD3+CD8+ ratio." (PMID 34239993, 2021). "To investigate the effect of HIV-1 subtype in CD4+ T cell counts we compared individuals with or without immunodeficiency and, among the immunodeficient, the ones with moderate or severe levels." (PMID 34845263, 2021). "Good's syndrome (GS) is an adult-onset immunodeficiency characterized by thymoma, hypogammaglobulinaemia, low or absent B‐cells, and an inverted CD4+/CD8+ T‐cell ratio." (PMID 34749670, 2021). "However, HIV-infected participants displayed a reduced CD4/CD8 ratio in blood (median 0.93, P = 0.004 vs. healthy controls), suggesting persistent immunodeficiency despite ART." (PMID 33848273, 2021). "The blood CD4+/CD8+ ratio was 0.7, suggesting immunodeficiency." (PMID 34243811, 2021). "Patients with ADCs were younger at onset of malignancies and had more rapid progression from HIV infection to malignancies diagnosis illustrated more aggressive clinical course compared with NADCs; lower CD4 counts and less suppression of HIVRNA that representative of advanced immunodeficiency." (PMID 34934097, 2021). "Persistent immune dysfunction may be the consequence of advanced immunocompromise prior to the start of ART, as defined by a low nadir CD4 cell count and inverted CD4:CD8 ratio." (PMID 33095853, 2021). "In the present study, although the percentages of CD4+ and CD8+ cells increased significantly after splenectomy, the ratio remained > 1.2, and this did not result in any diseases caused by immune dysfunction." (PMID 34711891, 2021). "In terms of baseline characteristics of enrolled patients, this study shows that CD4 T lymphocyte counts of PJP group and CMV-P group were both lower than 50 cells/mm3, highlighting the importance of cell-mediated immunodeficiency for the development of PJP and CMV-P." (PMID 33106188, 2020). "Immunological parameters were ranging from a moderate decrease in peripheral CD4+ T cells (F2 and G1) to severe combined immunodeficiency with virtually absent B- and T-cells (A1, B1, E1)." (PMID 32098969, 2020). "For example, AGMs can mount robust recall responses to MHC-II–restricted antigens in the CD4–CD8αα+ T cell compartment, and these animals do not suffer from any apparent immunodeficiency or autoimmunity." (PMID 32841214, 2020). "A similar case has been reported in a patas monkey, which exhibited no signs of immunodeficiency and yet had undetectable CD4 counts and was resistant to SIVagm exposure." (PMID 32841214, 2020). "Immunodeficiency with reduced ILC and CD4 T cell numbers and/or diminished ILC and CD4 T cell functions can result in insufficient immune response, which may cause chronic or repeated infections." (PMID 33126494, 2020). "The importance of CD4+ T cells, TNF-α, IFN-γ, IL-12p40, together with the IL-1/IL-1R1 pathway, in host resistance to intracellular Mtb infection is evident from animal models and human inherited and acquired immunodeficiencies." (PMID 32069329, 2020). "The patient was then assessed for risk factors for immunodeficiency: HIV serology was negative, CD4 count was normal (925/mm3) and the patient had never been on immunosuppressive drugs and had no history of organ transplantations or malignancy." (PMID 30626344, 2019). "In fact, these PBSnj eastern sites are located disproportionately in genes that differentiate the CD4 transcriptional response to SIV in a natural host species that tolerates the virus from a non-natural host species that develops immunodeficiency." (PMID 31765391, 2019).
Immunodeficiency (continued). "In this study, the co-expression of the positive costimulatory molecule ICOS and the negative costimulatory molecule PD-1 was examined on the CD4+ T cell membrane for the first time in patients with a CNS immune disease." (PMID 31575949, 2019). "The function deletion of the ZAP70 tyrosine kinase in humans can lead to a serious immunodeficiency, characterized by non-functional CD4+ T cells and lacking mature CD8+ T cells." (PMID 30497506, 2018). "(c) There is a form associated with immune deficiency, which occurs mainly in patients with HIV infection, regardless of the number of CD4 cells." (PMID 30286805, 2018). "In fact, HIV-infected persons are now recommended to initiate ART regardless of CD4 counts all over the world, and the objective of ART clearly turns to suppressing viral replication and preventing inflammation and immune deficiency." (PMID 29487595, 2018). "Conversely, HIV infection in the absence of immunodeficiency (CD4+ at > 200/uL) had only a minimal effect on the bacterial microbiome." (PMID 29933546, 2018). "Nevertheless, in our cohort of CVID patients, we did not observe any significant differences between absolute or relative counts of CD3+, CD4+, CD8+, and CD56+ cells measured at the time of diagnosis of immunodeficiency and those measured at the time of diagnosis of lymphoma." (PMID 30723478, 2018). "The frequency of NCI in such subjects who began ART one year after infection was similar to that in subjects who delayed treatment until their CD4+ counts declined to a predetermined low threshold, suggesting that mild HIV-NCI develops both independently of immunodeficiency and despite ART." (PMID 29879225, 2018). "This specific quality of PSP in cancer treatment is a powerful characteristic pertaining to our investigation, given that one outcome of HIV-1 pathogenesis is CD4+ depletion and diminished CD4+/CD8+ ratio in HIV-infected patients, suggesting immune dysfunction." (PMID 30116757, 2018). "Immunodeficiency in advanced cancer has been well documented and there is a significant trend of decreasing functional T cell populations (including CD4, CD8, CD4:CD8 ratio and naïve T cells) with cancer progression: this is associated with increased morbidity and mortality." (PMID 28384249, 2017). "National guidelines often, however, still contain CD4 count thresholds above which treatment is not initiated (CD4 counts being used as a marker of immunodeficiency level)." (PMID 27391129, 2016). "Naive B cells from patients with common variable immunodeficiency are markedly impaired in upregulating the costimulatory molecules CD86 and CD70 upon BCR cross-linking and the expression remained reduced even in the presence of autologous helper CD4+ T cells." (PMID 28116319, 2016). "A majority of the patient group completed blood work and exhibited laboratory changes consistent with the literature on HIV, including decreased total white blood cell counts, decreased CD4 cell counts (immunodeficiency), increased CD8 cell counts (immunosuppression) and a lower CD4:CD8 ratio." (PMID 26423806, 2015). "Overall, our study showed that MSCs differentially regulate the functional compartments of CD4+ and CD8+ T cells, which may differentially impact their therapeutic effect in immune disorders." (PMID 25559824, 2015). "The CD4:CD8 ratio can contribute to the immunological evaluation of treated patients in a long-term follow-up and may be applied for monitoring both immune dysfunction and viral reservoir size in immune-based clinical trials." (PMID 26130226, 2015). "Regardless of CD4 counts, OPT levels were diminished compared to previous reports of HIV-negative individuals, demonstrating humoral immune deficiency beginning at an earlier stage of infection." (PMID 25908995, 2015). "Their reduced IL-2 produced by CD4 T cells, and their reduced TNF-α by both CD4 and CD8 cells may explain the immunodeficiency of such HIV− patients, in addition to the finding of autoantibodies to IFN-γ." (PMID 25329064, 2014).